ROCK2 (Rho associated coiled-coil containing protein kinase 2)
Diseases named in the same sentence as ROCK2 in open-access papers (continued):
Sharing a sentence is not in itself a finding about the gene and the disease.
ischemic stroke (14 papers, 2017 to 2026). A stroke disorder caused by obstruction of blood flow to the brain, due to thrombotic (local blood clot formation) or embolic (due to a blood clot or other material traveling from another site) event. "It has been demonstrated that lncRNA-H19 can regulate ischemic stroke induced oxidative stress damage by increasing the expression of Rho-associated protein kinase 2 (Rock2) through the regulation of miR-148a, thus exerting a neuroprotective effect." (PMID 39399379, 2025). "In this study, we aimed to investigate the effects of inhibiting ROCK2 expression on synaptogenesis and neurogenesis in ischemic stroke using an shRNA-expressing adeno-associated virus (AAV) vector (AAV-sh.ROCK2)." (PMID 40537020, 2025). "Our study identified ROCK2 as a critical regulator of synaptogenesis and neurogenesis, highlighting it as a promising target to facilitate neuroprotection and regeneration in ischemic stroke." (PMID 40537020, 2025). "Specifically pertaining to ROCK2, the selective inhibition of ROCK2 after experimental ischemic stroke dose-dependently reduced infarct volumes and limited perfusion loss in male mice." (PMID 38164600, 2024). "RhoA/Rock2 upregulation contributes to neuroinflammation, blood-brain barrier dysfunction, axon growth inhibition and neuronal apoptosis following ischemic stroke." (PMID 37789455, 2023). "Our findings were consistent with previous reports showing upregulated NogoA/NgR and RhoA/ROCK-2, following ischemic stroke." (PMID 35559236, 2022). "In conclusion, our study confirmed that metformin exerts neuroprotective effects by regulating ischemic stroke-induced oxidative stress injury via the lncRNA-H19/miR-148a-3p/Rock2 axis." (PMID 31934270, 2019). "According to the results of this study, XSEC or EE monotherapy was sufficient to counteract ischemic stroke-induced high expression of NgR protein and NogoA/NgR/ROCK2 mRNA." (PMID 31920724, 2019). "Since t-PA-induced effects on the BBB are of particular relevance in the context of ischaemic stroke, it was crucial to assess selective ROCK-2 inhibition also under stroke-like conditions." (PMID 28510599, 2017). "Moreover, a recent study on stroke in mice models found a significant efficacy of apremilast on ischemic stroke outcomes by alleviating enhanced blood–brain barrier permeability and neuroinflammation through ROCK2 inhibition, suggesting its potential use as a therapeutic option for ischemic stroke." (PMID 38541719, 2024). "In summary, the novel PDE4 inhibitor APR showed significant efficacy on ischemic stroke outcomes by alleviating enhanced BBB permeability and neuroinflammation by inhibiting ROCK2." (PMID 35971637, 2022). "Taken together, our results demonstrate that APR showed significant efficacy on ischemic stroke outcomes by alleviating enhanced BBB permeability and neuroinflammation by inhibiting ROCK2." (PMID 35971637, 2022). "Of note, SLx-2119, that has 100-fold more selectivity towards ROCK2 than ROCK1, has been suggested to be a potential drug for the treatment of ischemic stroke, autoimmune disease and psoriasis." (PMID 30884801, 2019).
pancreatic cancer (14 papers, 2016 to 2025). "The Cancer Genome Atlas (TCGA) data analysis revealed that NT5E gene expression was strongly correlated with CD44 and ROCK1/ROCK2 gene expressions in pancreatic tumors, suggesting a link between CD73 and loss of epithelial features." (PMID 37851808, 2023). "In pancreatic cancer, Rho associated coiled coil containing protein kinase 2 (ROCK2) enhances the expression of ZEB1." (PMID 32664703, 2020). "Our results suggest that the high expression of phosphorylated ROCK2 causes ZEB1-mediated gemcitabine resistance in pancreatic cancer cells." (PMID 31783584, 2019). "Here, we provide evidence that Rho associated coiled-coil containing protein kinase 2 (ROCK2) maintains gemcitabine resistance in gemcitabine resistant pancreatic cancer cells (GR cells)." (PMID 31783584, 2019). "Elevated ROCK1 and/or ROCK2 expression was associated with shorter survival in human pancreatic cancer patients, while conditional ROCK activation in KrasG12D‐driven PDAC mice was sufficient to accelerate mortality." (PMID 28031255, 2017). "In pancreatic cancer, HNRNPC induced DNA damage repair and cancer-associated fibroblast activation through the RhoA/ROCK2-YAP/TAZ signaling pathway." (PMID 37469973, 2023). "In a separate project in our laboratory, we determined a role of ROCK2 in EMT-induced gemcitabine resistance in pancreatic cancer cells, and we revealed that ROCK2 induced increasement of ZEB1 expression and enhancement of DNA repair system." (PMID 35145081, 2022). "A previous study in our laboratory also demonstrated that ROCK2 facilitated gemcitabine-resistant pancreatic cancer cells to repair DNA damage." (PMID 35145081, 2022). "ROCK1 and ROCK2 expression was shown to be increased in human pancreatic tumors, in correlation with shorter patient survival." (PMID 34298680, 2021). "ROCK2 activation in non-invasive pancreatic cancer cells promotes their invasiveness in a collagen matrix in association with an increased ECM remodeling." (PMID 34298680, 2021). "ROCK2 was also identified as a driver molecule of EMT in gemcitabine-resistant pancreatic cancer cells, acting through the ROCK2/p38/sp1/Zinc-finger-enhancer binding protein 1 (ZEB1) signaling pathway." (PMID 33546351, 2021). "Mechanically, a novel sp1/p38/ZEB1 regulatory network was found to be involved in ROCK2-mediated gemcitabine resistance in pancreatic cancer cells." (PMID 31783584, 2019). "Our findings demonstrate the essential role of ROCK2 in EMT-induced gemcitabine resistance in pancreatic cancer cells and provide strong evidence for the clinical application of fasudil, a ROCK2 inhibitor, in gemcitabine-refractory PDAC." (PMID 31783584, 2019). "In our current study, we focused on exploring the role of ROCK2 in EMT-elicited resistance to gemcitabine in gemcitabine resistant pancreatic cancer (GR) cells." (PMID 31783584, 2019). "Nonetheless, the role of EMT in gemcitabine acquired resistance of pancreatic cancer cells and the involvement of ROCK2 in this process are still poorly understood." (PMID 31783584, 2019). "ROCK2 has been reported to mediate the chemoresistance in some cancers, however, the potential mechanism of ROCK2 in regulating chemotherapy resistance in pancreatic cancer is still unclear." (PMID 31783584, 2019). "In our study, we first discovered ROCK2 induced ZEB1-conferred gemcitabine resistance in pancreatic cancer cells." (PMID 31783584, 2019). "Our data suggest that targeting the ROCK2 signaling pathway appears to be a promising approach against gemcitabine resistance in pancreatic cancer." (PMID 31783584, 2019). "In this study, ROCK2 expression was found to increase with pancreatic cancer progression in human and KrasG12D‐driven mouse tumors." (PMID 28031255, 2017). "However, in pancreatic cancer and colon cancer, ROCK2 can promote the resistance of tumor cells to chemotherapy." (PMID 33153478, 2020).
pancreatic cancer (continued). "These demonstrated that targeting ROCK2 might be a potential strategy to improve the efficacy of various anticancer drugs in the treatment of refractory pancreatic cancer." (PMID 31783584, 2019). "The inhibition of the ROCK2 signal combined with gemcitabine treatment might appear to be a promising approach against gemcitabine resistance in pancreatic cancer." (PMID 31783584, 2019). "Furthermore, TCGA Research Network data also revealed significantly coordinated ROCK1 and ROCK2 mRNA expression in pancreatic cancers, consistent with an observed advantage associated with increased ROCK signaling in pancreatic cancer." (PMID 28031255, 2017). "Thus, the expression of EMT markers was partially regulated by ROCK2 in pancreatic cancer cells." (PMID 31783584, 2019). "Activation of ROCK1 or ROCK2 signalling induced significant changes in gene expression that could be used to determine how actomyosin contractility influences gene transcription in pancreatic cancer." (PMID 27824338, 2016). "We hope our study will provide new ideas for solving pancreatic cancer problems and translating ZFAS1/miR-3924/ROCK2 signalling knowledge into anticancer therapies." (PMID 32550827, 2020). "In this study, using a rigorously validated anti‐ROCK2 antibody, we found that ROCK2 expression increased with tumor progression in human PDAC and in mouse pancreatic cancer models." (PMID 28031255, 2017). "What role ROCK‐mediated actomyosin contractility might play in PDAC has not been established, nor has it been determined whether ROCK2 expression is altered in pancreatic cancer." (PMID 28031255, 2017).
chronic graft versus host disease (13 papers, 2018 to 2025). Chronic graft versus host disease (GVHD) is a complication that can occur after a stem cell or bone marrow transplant in which the newly transplanted donor cells attack the transplant recipient's body. "Belmudosudil, approved by the Food and Drug Administration in 2021 for chronic graft-versus-host-disease (cGVHD) treatment, is an inhibitor of Rho-associated coiled-coil containing protein kinase 2 (ROCK2)." (PMID 39483897, 2024). "Belumosudil is a first in class ROCK2-inhibitor approved by the FDA for the 3rd line treatment of chronic graft-versus-host disease (cGvHD)." (PMID 39809902, 2025). "For example, Belumosudil (originally a ROCK2 inhibitor for chronic GVHD) was predicted to insert into the LSD1 active site (near the FAD cofactor) and form stabilizing interactions analogous to known LSD1 inhibitors." (PMID 41301700, 2025). "Previous study found that ROCK2 inhibited chronic inflammation and fibrosis in cases of chronic graft-versus-host disease." (PMID 39455522, 2024). "Recent studies have highlighted the potential of ROCK2 inhibition as a promising therapeutic approach for immune-associated diseases such as systemic lupus erythematosus (SLE), IBD, and chronic GVHD." (PMID 37761990, 2023). "Moreover, the success of belumosudil in chronic graft-versus-host disease highlights the immunomodulatory potential of ROCK2-selective inhibition, paving the way for its application in other immune-mediated and fibrotic conditions." (PMID 41377066, 2025). "Belumosudil, an inhibitor of Rho-associated coiled-coil containing protein kinase 2 (ROCK2), was approved by the US Food and Drug Administration in 2021 for chronic graft-versus-host-disease (cGVHD) treatment, a disease with similar histopathological features as SSc." (PMID 40217251, 2025). "KD025 (SLx-2119), the first specific Rho-associated protein kinase 2 (ROCK2) inhibitor, is a potential new drug candidate currently undergoing several phase 2 clinical trials for psoriasis, idiopathic pulmonary fibrosis, chronic graft-versus-host disease, and systemic sclerosis." (PMID 32192179, 2020). "Belumosudil (trade name REZUROCK) is a preferential ROCK2 inhibitor, developed as an investigational drug and used in the ROCKstar Study78, and is currently FDA-approved for treatment of chronic graft-versus-host disease." (PMID 40253509, 2025).
psoriasis (13 papers, 2019 to 2025). An autoimmune condition characterized by red, well-delineated plaques with silvery scales that are usually on the extensor surfaces and scalp. "Rho-Associated Protein Kinase 2 (ROCK2) Inhibitors impact the inflammatory response and diminish the discharge of pro-inflammatory cytokines, arising as a promising choice for psoriasis treatment." (PMID 38793117, 2024). "Autoimmune diseases, such as systemic lupus erythematosus (SLE), psoriasis, and arthritis, are also characterized by an overexpression of the Rho-associated coiled-coil containing protein kinase 2 (ROCK2)." (PMID 37915324, 2023). "ADs, such as systemic lupus erythematosus, psoriasis, and arthritis, are also characterized by an overexpression of the Rho-associated coiled-coil containing protein kinase 2 (ROCK2), a serine/threonine kinase that can hyperactivate the JAK-STAT pathway." (PMID 37915324, 2023). "Rho-associated protein kinases (ROCK-2) inhibitors, such as belumosudil, represent a novel class targeting cytokine regulation and immune signaling pathways, with early evidence suggesting their potential to improve inflammatory conditions for psoriasis and PsA." (PMID 40004842, 2025). "In a clinical trial of a selective ROCK2 inhibitor in patients with psoriasis vulgaris, psoriasis area and severity index scores were reduced by 50% from baseline in 46% of patients, and epidermal thickness and T-cell infiltration of the skin were reduced." (PMID 33803946, 2021). "Inhibition of ROCK2 can block the role of IL-23/Th17 in psoriasis." (PMID 39296901, 2024). "ROCK2 inhibition, therefore, may be a promising strategy for the topical treatment of cutaneous inflammation in general and psoriasis in particular." (PMID 36890793, 2023). "Along with IL-36α, IL-17C, and IκBζ, ROCK2 could be an equally important factor in the pathogenesis of psoriasis, which may involve self-sustaining circuits between innate and adaptive immune responses via regulation of IL-36α and IL-36γ expression." (PMID 35563374, 2022). "Thus, the oral selective ROCK2 inhibitor improved the clinical symptoms of psoriasis patients by down-regulating the target Th17-driven autoimmune response without any adverse effects despite its systemic administration." (PMID 33803946, 2021). "Interestingly, ROCK2 inhibition by KD025 partially reverted the M5-driven inflammatory signature (clusters 5 and 11), suggesting that psoriasis-like inflammation in keratinocytes could be in part mediated by ROCK2." (PMID 36890793, 2023). "Therefore, targeting ROCK2 has a significant potential as a psoriasis therapy." (PMID 34371756, 2021). "In a phase II clinical trial of the ROCK2 inhibitor KD025, it lowered the levels of IL-17 and IL-23 in the blood of people with psoriasis." (PMID 39296901, 2024). "To confirm the effect of the ki16425 treatment on the epidermal expression of ROCK2 and p-AKT in IMQ-induced psoriasis-like mice, we performed immunohistochemical staining to analyze the expression of these molecules in skin tissues." (PMID 34639115, 2021). "Consistent with the results in HaCaT cells, the expression of ROCK2 and p-AKT was significantly increased in the skin of IMQ-induced psoriasis-like mice; however, the increase in the expression of these molecules was decreased by ki16425 treatment." (PMID 34639115, 2021). "In conclusion, we demonstrated that LPAR1/3 antagonist alleviates IMQ-induced psoriasis-like symptoms in mice, and in particular, LPAR1 signaling is involved in cell cycle progression via ROCK2/PI3K/AKT pathways in keratinocytes." (PMID 34639115, 2021).
Cognitive impairment (12 papers, 2016 to 2025). Abnormal cognition is characterized by deficits in thinking, reasoning, or remembering. "In this study, we have demonstrated that 9‐MF significantly prevented cognitive impairments, Aβ‐associated microglial over‐activation, and tau‐associated synaptic damage via cell‐specific inhibition of ROCK2 and GSK3β." (PMID 39563011, 2024). "Recently, we found that APC/C-Cdh1 targets Rock2 for proteasomal degradation in neurons, and that the loss of Cdh1 causes Rock2 stabilization and activation, triggering dendrite disruption, and dendritic spine and synapse loss in the adult brain following neurodegeneration and cognitive impairment." (PMID 35496276, 2022). "The schematic diagram showing the 9‐MF prevented long‐term cognitive impairments via cell‐specific inhibition of ROCK2 and GSK3β in APP/PS1 transgenic mice." (PMID 39563011, 2024). "PirB knockdown alleviated synaptic deficits and cognitive impairment after CSR by inhibiting the RhoA/ROCK2/LIMK1/cofilin signalling pathway." (PMID 36417104, 2023). "Additionally, intervention in the RhoA/ROCK2 signaling pathway via pharmacological approaches and genetic modification attenuates the phosphorylation of radixin, thereby mitigating cognitive impairments induced by sevoflurane." (PMID 38825816, 2024). "Rock2 inhibition rescues cognitive impairment induced by Aβ in vivo." (PMID 35496276, 2022). "ROCK inhibitors or knockdown of ROCK2 could attenuate the synaptic dysfunction and cognitive impairment induced by acrolein." (PMID 35315217, 2022). "Moreover, we identified that fasudil could mimic the beneficial effect of PirB knockdown and ameliorate synaptic deficits and cognitive impairment, which further demonstrated that the RhoA/ROCK2/LIMK1/cofilin signalling pathway is downstream of PirB in CSR." (PMID 36417104, 2023). "Finally, we investigated whether RhoA/ROCK2 pathway inhibition using fasudil, a widely used ROCK2 inhibitor, has therapeutic effects on cognitive impairment and synaptic deficits following CSR." (PMID 36417104, 2023). "Similarly, ROCK2 knockdown mice could partially alleviate acrolein‐induced cognitive impairment and synaptic damage." (PMID 35315217, 2022). "In addition, ROCK inhibitors or knocking down ROCK2 could attenuate the cognitive impairment and synaptic dysfunction induced by acrolein, suggesting that ROCK2 may be a potential target for the treatment of early AD." (PMID 35315217, 2022). "Moreover, ROCK2 protein levels are increased among mild cognitive impairment (MCI) and AD patients, suggesting that ROCK2 may contribute to synaptic loss in early disease stages." (PMID 33790742, 2021). "Moreover, we found that fasudil, a widely used ROCK2 inhibitor, could mimic the beneficial effect of PirB knockdown and ameliorate synaptic deficits and cognitive impairment, further demonstrating that PirB induced cognitive dysfunction after CSR via the RhoA/ROCK2/LIMK1/cofilin signalling pathway." (PMID 36417104, 2023). "It is worthy of pointing out that neither ROCK2 inhibitor nor knockdown of ROCK2 fully blocked the acrolein‐induced cognitive impairment although they have the benefit tendency." (PMID 35315217, 2022). "Altogether, these data reveal that CSR-mediated activation of the RhoA/ROCK2/LIMK1/cofilin signalling cascade via the PirB receptor may result in abnormal actin dynamics and actin rearrangement, ultimately leading to synaptic deficits and cognitive impairment." (PMID 36417104, 2023).
gastric cancer (12 papers, 2017 to 2025). A primary or metastatic malignant neoplasm involving the stomach. "ROCK2 (Rho associated coiled-coil containing protein kinase 2) upregulation has been described in human glioblastoma CSCs, in gastric cancer, as well as in ovarian cancer samples." (PMID 33557274, 2021). "ROCK2 in gastric cancer cell promoted tumor cell proliferation, metastasis and invasion." (PMID 37007126, 2023). "CircCUL2 was downregulated in gastric cancer and it could repress cancer malignant transformation and promote cisplatin sensitivity by sponging miR-142-3p and regulating ROCK2." (PMID 34983607, 2022). "We also found that mRNA expression levels of CDH1, CDKN1A, and EP300 were significantly reduced while those of RhoA, ROCK1, ROCK2, PIK3CA, and CCND1 were significantly increased in gastric cancers with reduced or loss of NKX6.3 expression compared to those in NKX6.3 positive cases." (PMID 30514953, 2018). "In addition, expression levels of CDH1, CDKN1A, and EP300 were reduced while expression levels of RhoA, ROCK1, ROCK2, PIK3CA, and CCND1 were increased in gastric cancer tissues with reduced or loss of NKX6.3 expression." (PMID 30514953, 2018). "Moreover, ROCK2 was regulated by miR-142-3p, and its reduced levels enhance ROCK2 expression, resulting in a DDP-resistant phenotype by reducing DDP-induced apoptosis in gastric cancer cells." (PMID 35444536, 2022). "Results showed that expression levels of NKX6.3, CDH1, CDKN1A, and EP300 were decreased while expression levels of NFκB p65, AICDA, CBFβ, APOBEC3A, APOBEC3B, RhoA, ROCK1, ROCK2, PIK3CA, and CCND1 were increased in CagA positive gastric cancers compared to those in CagA negative cases." (PMID 30514953, 2018).